ABCB1 (ATP binding cassette subfamily B member 1)
Diseases named in the same sentence as ABCB1 in open-access papers (continued):
Sharing a sentence is not in itself a finding about the gene and the disease.
thyroid cancer (5 papers, 2014 to 2022). "ABCG2 expression has been reported to be more highly expressed in a number of thyroid cancer cell lines above that of their NSP and ABCB1 has been reported to be expressed in the N-thy ori-3-1 and BCPAP cell lines." (PMID 35118633, 2022).
cholestasis (4 papers, 2018 to 2024). Impairment of the bile flow caused by obstruction within the liver, or outside the liver in the bile duct system. "DCF down-regulated many genes indicative of phospholipidosis, steatosis and cholestasis except for the ABCB1, which encodes for p-glycoprotein to aid in the elimination of xenobiotics, and WIPI1, which interacts with phospholipids." (PMID 30572671, 2018). "Here, we reviewed the leading molecular pathways between the DIC and ABCB1, ABCC2, ABCB11, and ABCB4 genes, the links with the other clinical forms of familial intrahepatic cholestasis, and, finally, the main cholestasis-inducing drugs." (PMID 36982896, 2023).
cognitive decline (4 papers, 2013 to 2026). "The ABCB1 3435C>T (rs1045642) variant significantly influences AD susceptibility and cognitive decline in Egyptians, with TT conferring risk and CC exerting a protective effect." (PMID 41882463, 2026). "Our study examined the impact of ABCB1 gene polymorphisms on cognitive decline in a cohort of individuals with MCI, AD, SCD, and cognitively healthy older adults." (PMID 40168071, 2025). "Although our study presents novel associations between ABCB1 polymorphisms and cognitive decline in MCI, we were unable to include a replication cohort within this study due to resource constraints." (PMID 40168071, 2025). "Our study extends this knowledge by demonstrating associations between specific ABCB1 polymorphisms in deep intronic regions and cognitive decline." (PMID 40168071, 2025). "Our findings highlight the significant role of ABCB1 polymorphisms in cognitive decline, particularly in language function, among individuals with amnestic MCI." (PMID 40168071, 2025). "The study aims to investigate the association between polymorphisms in the ABCB1 gene and cognitive decline in individuals with mild cognitive impairment (MCI), particularly focusing on language function." (PMID 40168071, 2025). "These polymorphisms could influence ABCB1 gene expression and function by potentially affecting transcription factor interactions and alternative splicing, suggesting their role in the cognitive decline observed in neurodegenerative diseases." (PMID 40168071, 2025). "A clinical study conducted in AD patients with mild cognitive deficits concluded that both doxycycline and rifampicin efficaciously reduce the cognitive decline in treated patients, possibly and partly via a mechanism involving ABCB1, as both molecules have been reported to induce ABCB1 expression." (PMID 23494712, 2013). "The association of ABCB1 polymorphisms with language impairments in MCI might be influenced by the role of GRα in these processes, highlighting the importance of genetic factors in the cognitive decline observed in neurodegenerative diseases." (PMID 40168071, 2025). "Taking into account all these considerations, the concept that restoring ABCB1 at the BBB could be a valid therapeutic strategy to lower Aβ brain load, reduce cognitive decline, delay onset, and slow progression of AD has to be critically evaluated." (PMID 29317984, 2017).
dyslipidemia (4 papers, 2020 to 2024). "Xinjiang is a multi-ethnic area; however, little is known about the prevalence of dyslipidemia and gene polymorphisms of ABCB1 and SLCO1B1 in minority groups with CHD." (PMID 34563206, 2021). "Since the expression levels of ABCG2 are primarily determined by rs2231142, it indicates that the rs2231142 variant may induce dyslipidemia by modulating ABCB1 expression." (PMID 38589776, 2024). "In addition to ABCB1, we also analyzed variants in APOE and UGT1A7 pharmacogenes, associated with ritonavir induced dyslipidemia and hyperbilirubinemia, respectively." (PMID 33312066, 2020).
ependymoma (4 papers, 2019 to 2024). A WHO grade II, slow growing tumor of children and young adults, usually located intraventricularly. "Together, these novel prognostic associations have two implications for ependymoma therapy for the 0–19 age group, stratified according to ABCB1 status." (PMID 31311995, 2019). "Here we set out to determine the role of the multidrug efflux transporter ABCB1/P-glycoprotein in paediatric ependymoma using a panel of ependymoma derived cell lines and analyses of two clinical trial cohorts." (PMID 31311995, 2019). "To this end, we have been able to demonstrate that 4 out of the 5 ependymoma derived cell lines tested expressed ABCB1 by quantitative PCR." (PMID 31311995, 2019). "Another potential advantage of ABCB1 inhibition would be increased drug uptake at the blood-tumour barrier, since we have also been able to detect ABCB1 expression in the blood vessels supplying ependymomas." (PMID 31311995, 2019). "Using ABCB1 inhibitors alone we were able to significantly reduce the migration of ependymoma cells in a wound healing assay (p ≤ 0.001) in both cell lines." (PMID 31311995, 2019). "Clonogenic survival was assessed in BXD-1425EPN in response to three ABCB1 substrates that are commonly used in the treatment of paediatric ependymoma." (PMID 31311995, 2019). "ABCB1 gene expression was observed in 4 out of 5 paediatric ependymoma cell lines and increased in stem cell enriched neurospheres." (PMID 31311995, 2019). "On this basis ABCB1 is one of the key biomarkers being evaluated in the ongoing SIOP ependymoma II trail through the BIOMECA consortium." (PMID 31311995, 2019). "Hence, ABCB1 expression in a small sub-population of tumour cells is able to confer a drug resistant phenotype in paediatric ependymoma patients in CNS9204." (PMID 31311995, 2019). "Furthermore, ABCB1 inhibition may increase the efficacy of adjuvant chemotherapy in almost a third of paediatric ependymomas (in total 32% of patients were ABCB1 positive over both trials)." (PMID 31311995, 2019). "In order to address the hypothesis that ABCB1 was functioning as a multidrug transporter in a subpopulation of ependymoma cancer stem cells, we compared outcome in paediatric patients from a primary infant chemotherapy trial (CNS9204) to those from a primary radiotherapy trial (CNS9904)." (PMID 31311995, 2019). "ABCB1 is a predictive marker of chemotherapy response in ependymoma patients and vardenafil, currently used to treat paediatric pulmonary hypertension in children, could be repurposed to reduce chemoresistance, migration and invasion in paediatric ependymoma patients at non-toxic concentrations." (PMID 31311995, 2019). "ABCB1 gene expression was investigated in 3 previously published (EPN126, BXD-1425EPN27 and DKFZ-EP128) and 2 newly established (EPN7 and EPN7R) ependymoma cell lines." (PMID 31311995, 2019). "In ependymoma, the high expression level of ABCB1 was observed in the CSC population, and the inhibition of ABCB1 by vardenafil or verapamil could potentiate the response to chemotherapeutic drugs of vincristine, etoposide, and methotrexate." (PMID 37370764, 2023).
esophageal squamous cell carcinoma (4 papers, 2014 to 2024). Esophageal squamous cell carcinoma (ESCC) is a type of esophageal carcinoma (EC) that can affect any part of the esophagus, but is usually located in the upper or middle third. "In this study, we demonstrated that ABCB1 efflux transporter expression is significantly higher in adenocarcinoma of the esophagus compared to squamous cell carcinoma of the esophagus." (PMID 34858183, 2021).
Ewing sarcoma (4 papers, 2012 to 2020). A small round cell tumor that lacks morphologic, immunohistochemical, and electron microscopic evidence of neuroectodermal differentiation. "Interestingly, in a panel of 6 Ewing sarcoma cell lines, high basal expression levels of ABCC4 were associated with enhanced sensitivity to SP-2509 (R2 = 0.4321) with the converse for ABCB1, high basal expression was associated with decreased sensitivity (R2 = 0.4249)." (PMID 30559927, 2018). "Indeed, several studies have shown that Ewing sarcoma cell lines and tumors basally express high levels of the drug-efflux proteins MDR1 (P-glycoprotein), MRP1, ABCB1 and ABCG2." (PMID 30559927, 2018). "Moreover, this strong synergy was absent in a low-ABCB1 expressing Ewing sarcoma cells line." (PMID 28596528, 2017).
liver fibrosis (4 papers, 2018 to 2023). "The mRNA levels of CYP2B6, CYP3A4, and ABCB1 was quantified and compared between the groups, along with the analysis of liver fibrosis and inflammation levels." (PMID 37512019, 2023). "An additional aim was to analyze the association between the degree of liver fibrosis, level of liver inflammation, and potential impact of applied antiviral and antiretroviral therapeutics on the expression of CYP3A4, CYP2B6, and ABCB1 transporters in this patient population." (PMID 37512019, 2023). "Combining the findings of our research, we infer that ABCB1 might be a novel therapeutic target to liver fibrosis, although this hypothesis need to be verified in further study." (PMID 30923657, 2019). "However, there are currently no studies reporting that ABCB1, P glycoprotein or Zosuquidar is associated with liver fibrosis." (PMID 30923657, 2019). "Among the target genes corresponding to these compounds, we found that HTR2B, ABCB1, and ALOX5 were significantly up-regulated in HBV and HCV related liver fibrosis datasets (Data not show)." (PMID 30923657, 2019).
myocardial infarction (4 papers, 2016 to 2025). Gross necrosis of the myocardium, as a result of interruption of the blood supply to the area, as in coronary thrombosis. "This research highlights key genes associated with mitochondrial oxidative stress—VCL, ABCB1, JAK2, KDR, NGF—that show differential expression in DCM and myocardial infarction." (PMID 40217309, 2025).
psoriasis (4 papers, 2018 to 2025). An autoimmune condition characterized by red, well-delineated plaques with silvery scales that are usually on the extensor surfaces and scalp. "In patients with psoriasis, ABCB1 gene polymorphisms play a significant role in the efficacy of MTX." (PMID 40626260, 2025). "In patients with psoriasis, ABCB1 gene polymorphisms have a significant impact on the therapeutic efficacy of MTX." (PMID 40626260, 2025). "In this study, we identified the SNPs in the ABCB1 gene as genetic variants with clinically relevant effects on the psoriasis response of cyclosporine." (PMID 36432633, 2022). "Further studies of different populations are required in order to explore the influence of these variants of the ABCB1 gene on the effectiveness of the cyclosporine treatment in psoriasis patients." (PMID 36432633, 2022). "In conclusion, we demonstrated a strong association between the cyclosporine therapy in psoriasis and the ABCB1 C1236T, G2677T/A and C3435T SNPs." (PMID 36432633, 2022). "In a study involving 84 Greek psoriasis patients, ABCB1 C3435T polymorphism contributed to a lower ABCB1 activity." (PMID 36432633, 2022). "In patients with psoriasis, 3435C > T polymorphism in ABCB1 was shown to be associated with response to cyclosporine, which is a substrate of P-gp." (PMID 29948283, 2018). "Stratification of individuals according to the HLA-C allele status revealed significant associations between HLA-Cw6+ patients and treatment outcomes in arthritis-free psoriasis patients, while the CsA-associated ABCB1 rs1045642 SNP was additionally incorporated into significant predictive models." (PMID 37108251, 2023). "Therefore, when using MTX-containing traditional Chinese medicine in patients with psoriasis, the polymorphisms of the ABCB1 gene may need to be taken into consideration." (PMID 40626260, 2025). "The present study aimed to analyze the effect of ABCB1 polymorphisms on the response to cyclosporine therapies in Russian psoriasis patients who have an ABCB1 genotype status." (PMID 36432633, 2022). "The ABCB1 T-129C, G1199A, C1236T, G2677T/A and C3435T SNPs in the 168 patients with psoriasis were genotyped by PCR-RFLP (polymerase chain reaction-restriction fragment length polymorphism) and TaqMan SNP genotyping assays." (PMID 36432633, 2022). "The majority of pharmacogenetic studies have focused on the mechanism of action of CsA, with the first work reporting a significant association between the rare ABCB1 rs1045642 allele and negative CsA response in 84 psoriasis patients." (PMID 37108251, 2023). "The aim of this research was to evaluate the effect of ABCB1 genetic variants that could affect the response to a cyclosporine treatment in Russian psoriasis patients with the ABCB1 genotype status." (PMID 36432633, 2022). "The expression of ABCB1 in psoriasis lesional skin was detected to be significantly decreased." (PMID 36432633, 2022). "The absorption of CsA is highly variable in psoriasis patients which can be explained by the function and expression of the multidrug efflux transporter P-gp P-glycoprotein (MDR1 Multidrug Resistance Protein 1, ABCB1 ATP Binding Cassette Subfamily B Member 1)." (PMID 36432633, 2022).
Skin rash (4 papers, 2016 to 2025). A red eruption of the skin. "There was also a marginal association between ABCB1 (rs1045642) and gefitinib-induced skin rashes (p = 0.068)." (PMID 41199076, 2025). "For the skin rash ADR, the ABCB1 gene rs1128503 with the polymorphism 1236C>T (CT + TT group versus CC group) was significantly associated with the presence of skin rash development (OR = 6.99; 95% CI: 1.61–30.30; p = 0,009; and I2 = 0%)." (PMID 38790220, 2024). "Correlation between CYP1A2 polymorphisms and severity of skin rash was observed, together with the correlation between the development of diarrhea and SNPs in ABCB1 and CYP3A5." (PMID 32457635, 2020). "The polymorphism of CYP1A2 was significantly associated with the severity of skin rash, and the development of diarrhea was associated with SNPs in ABCB1 and CYP3A5." (PMID 32457635, 2020). "The polymorphisms of CYP1A2 plays an important role in the severity of skin rash, and the development of diarrhea was associated with SNPs in ABCB1 and CYP3A5." (PMID 32457635, 2020). "A four-genes model (rs884225 in EGFR 3′UTR, rs7787082 in ABCB1 intron, rs38845 in MET intron and rs3803300 in AKT1 5′UTR) was associated with TKIs induced ADRs and skin rash." (PMID 26988277, 2016). "Altogether, this systematic review indicates that genetic variants of ABCB1 (rs1045642 and rs1128503) and ABCG2 (rs2231142) transporters are likely to exhibit clinical implications relating to the presence of adverse reactions (skin rash and diarrhea) to gefitinib in patients with NSCLC." (PMID 38790220, 2024).
temporal lobe epilepsy (4 papers, 2016 to 2025). A localization-related (focal) form of epilepsy characterized by recurrent seizures that arise from foci within the temporal lobe, most commonly from its mesial aspect. "Luciferase assays verified that an miR-1304-3p/ABCB1 axis existed and might contribute to the mechanisms of drug resistance in temporal lobe epilepsy." (PMID 41431653, 2025). "In fact, studies showed an increase in ABCB1 and ABCC2 protein expression in endothelial cells from temporal lobe blood vessels of patients with refractory MTLE, and a higher ABCB1 protein activity was observed in hippocampus of patients with pharmacoresistant temporal lobe epilepsy." (PMID 28052106, 2017).
thrombosis (4 papers, 2012 to 2024). "The distribution of ABCB1 C3435T genotypes for patients with and without thrombosis." (PMID 23056288, 2012).
alcohol (3 papers, 2013 to 2017). "This study provides evidence for three alcohol-induced ONFH susceptibility genes (NOS3, ABCB1 and IL23R) in Chinese males and polymorphisms of them may be associated with alcohol-induced ONFH risk." (PMID 28422712, 2017). "Furthermore, a protective factor associated with treatment response was the ABCB1 2677T allele and the CYP2B6 785G allele, and the risk factors were HCV infection, alcohol problems, and diagnosis with a psychiatric disease." (PMID 24455721, 2013). "In our robustness check, the association between ABCB1 variation and AAB was attenuated after controlling for alcohol dependence, but did not disappear (P=1.3 × 10−2)." (PMID 25918995, 2015).
atherosclerosis (3 papers, 2014 to 2025). A disease characterized by the build-up of fatty material and calcium deposition in the arterial wall resulting in partial or complete occlusion of the arterial lumen. "In addition, elevated levels of mRNA ABCB1 were found in the tissues in atherosclerosis, which allows us to suggest a role of ABCB1 in the development of atherosclerotic lesions in vivo." (PMID 34201488, 2021). "Indeed, the key genes enriched in the cholesterol binding pathway have links to cholesterol efflux (ABCG1), inflammation, and atherosclerosis (ABCB1 and APOA2)." (PMID 24763700, 2014).
brain cancer (3 papers, 2023 to 2024). A primary or metastatic malignant neoplasm affecting the brain. "While many anticancer drugs show promising effects against different brain cancer cell lines in vitro, their efficacy in vivo and in clinical trials has been marginal at best, in large part due to ABCB1/ABCG2-mediated efflux at the blood-brain barrier." (PMID 36973040, 2023). "Furthermore, several studies showed that S1P stimulates the activity of p-glycoprotein through activation of Abcb1 transport by S1PR1 and S1PR3 receptors at the brain cancer cell surface (RBE4)." (PMID 38419070, 2024).
cholangiocarcinoma (3 papers, 2013 to 2022). A carcinoma that arises from the intrahepatic biliary tree (intrahepatic cholangiocarcinoma) or from the junction, or adjacent to the junction, of the right and left hepatic ducts (hilar cholangiocarcinoma). "As such, new developments of targeted therapies and chemosensitizers, such as those targeting ABCB1 efflux pumps are crucial for improving future treatment options for cholangiocarcinoma patients." (PMID 35463361, 2022).
chronic kidney disease (3 papers, 2018 to 2025). Impairment of the renal function secondary to chronic kidney damage persisting for three or more months. "Indoxyl sulfate (IS, one of microbiota-derived toxins) was demonstrated to regulate hepatic P-gp (ABCB1) via AhR in rodent and cell culture models of chronic kidney disease (CKD)." (PMID 39713147, 2024).
gastrointestinal stromal tumor (3 papers, 2014 to 2022). "The similar effect of BGJ 398 was observed for ABCB1-overexpressing gastrointestinal stromal tumor cells (GIST-T-1 Tx-R)." (PMID 35327403, 2022). "Thus, we also included in our study ABCB1-overexpressing gastrointestinal stromal tumor (GIST T-1 Tx-R) cell subline, which was also generated in our laboratory." (PMID 35327403, 2022). "Furthermore, ABCB1 has been found to be overexpressed in different cancers, such as gastrointestinal stromal tumor (GIST), non-small cell lung cancer (NSCLC), fallopian tube, ovarian and thyroid cancer." (PMID 26716507, 2016). "Considerable evidence suggested that there are strong relationships between the overexpression of ABCB1 and various cancers, like advanced gastrointestinal stromal tumor (GIST), non-small cell lung cancer (NSCLC), fallopian tube, ovarian and thyroid cancer." (PMID 25268163, 2014).
head and neck squamous cell carcinoma (3 papers, 2021 to 2025). A squamous cell carcinoma that arises from any of the following anatomic sites: lip and oral cavity, nasal cavity, paranasal sinuses, pharynx, larynx, and salivary glands. "In patients with head and neck squamous cell carcinoma, high expressions of ABCB1 and ABCC1 were associated with favorable survival." (PMID 33531973, 2021). "We analyzed the effects of melatonin (1 mM) on head and neck squamous cell carcinoma cell lines (CAL 27 and SCC‐9) overexpressing ABCB1 and exhibiting increased resistance to cisplatin (CDDP) compared to their parental cells." (PMID 41189280, 2025).